RNU4-15P (RNA, U4 small nuclear 15, pseudogene)
Gene: Small nuclear RNA gene on chromosome 9 (83,596,444 to 83,596,584, reverse strand). Ensembl gene ENSG00000199483.
Homologues: Orthologues: macaque U4 (87% identical), rabbit U4 (70% identical), dog U4 (64% identical), pig U4 (63% identical), tropical clawed frog U4 (62% identical), rat LOC120093500 (62% identical), mouse Gm23459 (55% identical). Paralogues in human: RNU4-10P (72% identical), RNU4-49P (72% identical), RNU4-83P (70% identical), RNU4-81P (70% identical), RNU4-90P (70% identical), RNU4-17P (69% identical), RNU4-36P (69% identical), RNU4-28P (68% identical), RNU4-32P (68% identical), RNU4-50P (67% identical), RNU4-24P (66% identical), RNU4-66P (66% identical), and 81 more.